RRP1B (ribosomal RNA processing 1B)
Diseases named in the same sentence as RRP1B in open-access papers:
RRP1B is named in the same sentence as 23 diseases in open-access papers, as found by Europe PMC text mining. Sharing a sentence is not in itself a finding about the gene and the disease. The quoted sentences say what the papers report.
breast carcinoma (11 papers, 2007 to 2024). "The significance of RRP1B was underscored by the discovery that germline polymorphisms (SNPs) within the human RRP1B consistently correlate with clinical breast cancer outcomes and survival." (PMID 38610928, 2024). "Several interactors in this group were also identified as substrates, including the RNA helicase DDX10, the guanine nucleotide binding protein GNL1 and RRP1B, a ribosomal RNA processing protein which has been linked as a susceptibility marker in breast cancer." (PMID 29214152, 2017). "They provided the evidences that BRD4 long isoform reduced metastasis, however short isoform enhanced metastasis in breast cancer through interactions with the metastasis susceptibility protein RRP1B and SIPA1." (PMID 25603177, 2015). "Furthermore, we show that germline-encoded RRP1B variation is associated with markers of outcome in two breast cancer populations." (PMID 18081427, 2007). "Finally, constitutional polymorphism within RRP1B was found to be significantly associated with tumor progression in two independent breast cancer cohorts." (PMID 18081427, 2007). "Specifically, the study revealed a connection between the T allele of the RRP1B SNP (rs9306160) and a more favorable prognosis in MFS among breast cancer patients." (PMID 38610928, 2024). "Expression of RRP1B, and the activity of RRP1B expression, was investigated to be higher in low-metastatic mice inbred strains with mammary cancer compared to high-metastatic strains." (PMID 38610928, 2024). "The ectopic expression of RRP1B inhibited tumor growth and metastasis in the highly metastatic mouse mammary tumor cell line." (PMID 38610928, 2024). "RRP1B is a nuclear protein that has been identified as a breast cancer metastasis suppressor through heterochromatinization at specific loci with hypermethylation at histone 3, which represses the expression of certain genes." (PMID 31717460, 2019). "The results showed that ribosomal RNA processing protein 1B (RRP1B), a metastatic modulator in breast cancer, exhibited the most changes (up to 15-fold) after a three day-knockdown of DOCK1 in BT-549 cells (data not shown)." (PMID 31717460, 2019). "Due to the known roles of RRP1B in breast cancer progression and metastasis, further efforts were focused on validating its interaction with BRD4-SF." (PMID 24260471, 2013). "Specifically, we demonstrate that a microarray gene expression signature indicative of differential RRP1B expression predicts breast cancer-specific survival." (PMID 18081427, 2007). "We have used a dual approach to try to address the importance of RRP1B in human breast cancer progression." (PMID 18081427, 2007). "Further research, however, is clearly needed to fully explore the role of Rrp1b and Sipa1 in human breast cancer and other tumor types." (PMID 18081427, 2007). "RRP1B SNP analysis was performed in a second small pilot cohort consisting of 248 surgical breast cancer patients (58% African-American, 42% Caucasian) from the greater Baltimore area to attempt to replicate the findings of the initial cohort study." (PMID 18081427, 2007). "Differential RRP1B functionality also appears to play an important role in human breast cancer progression." (PMID 18081427, 2007). "Additionally, the variation in RRP1B expression within a highly metastatic mouse mammary tumor cell line was found to modify progression." (PMID 38610928, 2024). "Furthermore, a gene signature induced by ectopic expression of Rrp1b in tumor cells predicted survival in a human breast cancer gene expression dataset." (PMID 18081427, 2007). "If RRP1B is at least partially responsible for the presence of the ECM components of metastasis predictive gene signatures, it would suggest that a signature of RRP1B activation or expression might also be predictive of breast cancer survival." (PMID 18081427, 2007).
breast carcinoma (continued). "The first of these approaches was to use data derived from microarray expression analysis of the Mvt-1/Rrp1b cells to address one of the central goals of our research: the translation of experimental data from mouse models of human breast cancer into potentially clinically relevant observations." (PMID 18081427, 2007). "The pilot epidemiology data, while consistent with the possibility of role of RRP1B in breast cancer progression, does not distinguish between causal polymorphisms and polymorphisms in high linkage disequilibrium (LD) with the causal variant." (PMID 18081427, 2007). "In summary, these data suggest that Rrp1b may be a germline-encoded metastasis modifier in both mice and humans, which leads to the possibility that knowledge of RRP1B functionality and variation in breast cancer might facilitate improved assessment of prognosis." (PMID 18081427, 2007). "Furthermore, we demonstrate that Rrp1b expression levels are modulated by germline variation in mice with differing metastatic propensities, and that variation of Rrp1b expression in a highly metastatic mouse mammary tumor cell line modifies progression." (PMID 18081427, 2007). "Further experimentation demonstrated that ectopic expression of Rrp1b in two highly metastatic mammary tumor cell lines and a mouse fibroblast cell line modulates ECM gene expression, a finding concurrent with our initial hypothesis that Rrp1b is indeed the chromosome 17 ECM eQTL." (PMID 18081427, 2007). "RRP1B can upregulate the expression of claudin-1 by depleting DOCK1 and increase cell viability and motility of claudin-low breast cancer cells." (PMID 38610928, 2024). "This study demonstrated that DOCK1 mediates growth and motility through down-regulated claudin-1 expression via the RRP1B–DNMT–claudin-1 pathway and that claudin-1 serves as an important effector in DOCK1-mediated cancer progression and metastasis in claudin-low breast cancer cells." (PMID 31717460, 2019). "Furthermore, RRP1B mediated DOCK1 depletion, which up-regulated claudin-1 expression, cell viability, and motility in claudin-low breast cancer cells." (PMID 31717460, 2019).
pulmonary hypertension (2 papers, 2022 to 2024). Increased pressure within the pulmonary circulation due to lung or heart disorder. "Silencing RRP1B reduces inflammation and apoptosis, highlighting its potential significance in pulmonary hypertension pathology." (PMID 38610928, 2024). "The key pathogenic features of pulmonary hypertension are endothelial apoptosis and vascular inflammation, which are caused by the down-regulation of Amphiregulin, accompanied by HIF-1a and BAD-mediated up-regulation of the target genes such as RRP1B, PHB2, and NCOA6." (PMID 35732465, 2022).
triple-negative breast carcinoma (2 papers, 2022 to 2026). An invasive breast carcinoma which is negative for expression of estrogen receptor (ER), progesterone receptor (PR), and human epidermal growth factor receptor 2 (HER2). "Elevated DOCK1 expression enhances tumor cell migration via pathways involving RRP1B and Claudin-1, particularly in claudin-low and triple-negative breast cancer cells." (PMID 41516402, 2026).
acute myeloid leukemia (1 paper, 2016). Acute myeloid leukemia (AML) is a group of neoplasms arising from precursor cells committed to the myeloid cell-line differentiation. "Another confirmed lncRNA was RRP1B (8th in the prediction results), which showed differential expression between acute myeloid leukemia patients with different treatments." (PMID 27517318, 2016).
bladder cancer (1 paper, 2025). "In the RRP1B high-expression group, enrichment was observed in cell cycle, sulfur metabolism, thyroid cancer, bladder cancer, and non-small cell lung cancer pathways." (PMID 41246341, 2025).
cervical cancer (1 paper, 2024). A primary or metastatic malignant neoplasm involving the cervix. "In the present study, we examined the associations between five functional SNPs in the RRP1B gene and the clinicopathological profiles and survival rates in a cohort of Lithuanian women with cervical cancer." (PMID 38610928, 2024). "Our investigation indicates a potential link between RRP1B polymorphisms and the pathomorphological features of cervical cancer, as well as disease outcomes." (PMID 38610928, 2024). "We analyzed five RRP1B polymorphisms in 172 cervical cancer patients to understand their associations with disease characteristics and survival." (PMID 38610928, 2024). "Based on these abundant and trending findings, it can be anticipated that RRP1B SNPs play a role in influencing the aggressiveness of cervical cancer and and the risk of metastasis." (PMID 38610928, 2024). "Regrettably, our data could not be compared with that of other researchers, as we were unable to find publications specifically investigating and analyzing RRP1B polymorphisms in cervical cancer cases." (PMID 38610928, 2024). "Through a comprehensive analysis of 172 cervical cancer patients, we evaluated five RRP1B single nucleotide polymorphisms (SNPs) (rs2838342, rs7276633, rs2051407, rs9306160, and rs762400) for their associations with clinicopathological features and survival outcomes." (PMID 38610928, 2024). "All investigated RRP1B polymorphisms (rs2838342, rs7276633, rs2051407, rs9306160, and rs762400) in our study have the potential to serve as markers for clinical characteristics and prognosis in cervical cancer." (PMID 38610928, 2024). "This study investigates the involvement of the ribosomal RNA processing 1 homolog B (RRP1B) gene in metastasis regulation in cervical cancer." (PMID 38610928, 2024). "This research provides critical insights for future investigations and underscores the importance of incorporating RRP1B SNP detection into prognostic-assessment tools for accurate prediction of disease outcomes in cervical cancer." (PMID 38610928, 2024). "Our findings underscore the clinical relevance of RRP1B SNPs as prognostic markers in cervical cancer, shedding light on the intricate interplay between genetic factors and disease-progression dynamics." (PMID 38610928, 2024). "Recognizing the potential impact of germline polymorphisms on disease pathomorphological features and disease progression, we examined five single nucleotide polymorphisms (SNPs) (rs2838342, rs7276633, rs2051407, rs9306160, and rs762400) within the RRP1B gene among cervical cancer patients." (PMID 38610928, 2024). "In the future, SNP detection in RRP1B may serve as a predictive tool for assessing the clinical manifestations and prognoses of cervical cancer." (PMID 38610928, 2024). "Importantly, our decision to study RRP1B stems from a comprehensive approach aimed at elucidating the full spectrum of genetic factors contributing to cervical cancer development and progression." (PMID 38610928, 2024). "This article delves into the role of the ribosomal RNA processing 1 homolog B (RRP1B) gene in metastasis regulation, investigating its implications in human cervical cancer." (PMID 38610928, 2024).
Down syndrome (1 paper, 2024). "The expression of RRP1B was analyzed in leucocytes of individuals with Down’s syndrome (DS)." (PMID 38610928, 2024).
gastric cancer (1 paper, 2024). A primary or metastatic malignant neoplasm involving the stomach. "The expression level of RRP1B was significantly reduced in 76 early gastric cancer tissues compared with normal cases in the Chinese study." (PMID 38610928, 2024). "RRP1B has been represented as a likely biomarker for early gastric cancer." (PMID 38610928, 2024).
Hypertension (1 paper, 2025). The presence of chronic increased pressure in the systemic arterial system. "RRP1B is a target gene that interacts with the beta-blocker drug Atenolol, which is sometimes used to treat hypertension and chronic angina." (PMID 40537477, 2025).
laryngeal squamous cell carcinoma (1 paper, 2024). A squamous cell carcinoma that arises from the larynx. "The other study involved the analysis of 54 pairs of laryngeal tumor and adjacent normal tissues, it was revealed that RRP1B is significantly downexpressed in laryngeal squamous cell carcinoma." (PMID 38610928, 2024).
oral squamous cell carcinoma (1 paper, 2024). "There is a potential link between ALY (Aly/REF export factor), RRP1B, and metastasis in oral squamous cell carcinoma (OSCC)." (PMID 38610928, 2024).
retinoblastoma (1 paper, 2018). A malignant tumor that originates in the nuclear layer of the retina. "The results of microarray analysis showed that lncRNAs HOTAIR, CCAT1, DNM3OS, HIF1A‐AS1, MEG3 and 7SK expressions were up‐regulated, and lncRNAs PCAT1, MIR31HG, BCAR4, RRP1B and H19 were down‐regulated within retinoblastoma tissues." (PMID 30030888, 2018).
Sepsis (1 paper, 2024). Sepsis is defined as life-threatening organ dysfunction caused by a dysregulated host response to infection. "It has been identified that RRP1B participates in the pathogenetic process of sepsis by regulating the activation and differentiation of lymphocytes." (PMID 38610928, 2024).
systemic sclerosis (1 paper, 2007). A chronic disorder, possibly autoimmune, marked by excessive production of collagen which results in hardening and thickening of body tissues. "Differential expression of RRP1B has been reported in fibroblasts from patients with systemic sclerosis, an autoimmune disorder characterized by dysregulation of a variety of ECM genes, including procollagens I, III, and VI, consistent with our results." (PMID 18081427, 2007).
tumor (9 papers, 2007 to 2026). "Alterations in cell adhesion induced by RRP1B suppressed tumor growth and metastasis and are associated with the expression of extracellular matrix genes and SPIA1 (serpin peptidase inhibitor, clade A, member 1)." (PMID 31717460, 2019). "This integrated approach suggests that Rrp1b is a novel tumor progression and metastasis susceptibility locus in both mice and humans." (PMID 18081427, 2007). "Polymorphisms in several other tumor cell autonomous metastasis susceptibility genes identified in our laboratory including Sipa1, Rrp1b, and Brd4 are prognostic only in ER+ patients, and stable expression of Brd4 can also differentially regulate the Tpx2 network." (PMID 22693453, 2012). "Furthermore, functional data provides evidence that Rrp1b regulates ECM gene expression, and that a nonsynonymous SNP in RRP1B is associated with tumor progression and disease-specific survival in pilot epidemiology experiments." (PMID 18081427, 2007). "A significant survival difference was observed implying that the level of activation of RRP1B or RRP1B-associated pathways within a tumor, presumably because of either somatic mutation or germline polymorphism, may be an important determinant of the overall likelihood of relapse and/or survival." (PMID 18081427, 2007). "Further experimentation demonstrated that RRP1B interacts with protein phosphatase 1 (PP1), whose functions are implicated in tumorigenesis, the tumor microenvironment, and the metastatic cascade, and it regulates nucleolar phosphorylation signaling." (PMID 38610928, 2024). "Both tumor growth and lung surface metastasis were significantly reduced in Mvt-1/Rrp1b clonal isolates." (PMID 18081427, 2007). "It is also evident that further work will be necessary to define the complex microenvironmental relationships that modulate ECM gene expression in bulk tumor tissue and their relationship to overall levels of Rrp1b activation." (PMID 18081427, 2007). "Expression of the RRP1B signature in bulk primary tumor tissue predicted outcome in patients that were both LN negative and LN positive and patients with ER positive tumors (respectively)." (PMID 18081427, 2007). "Ectopic Expression of RRP1B reduced tumor growth and metastatic potential." (PMID 38610928, 2024). "RRP1B is another gene that significantly correlated with poor survival in TCGA, yet the gene is believed to interact with metastasis modifier genes to induce tumor suppression." (PMID 27959953, 2016). "The 295 samples of the Rosetta data set were clustered into one of two groups representing high and low levels of RRP1B activation in primary tumor samples in an unsupervised manner based on the 196 significantly differentially expressed RRP1B signature genes on the Hu25K chip." (PMID 18081427, 2007). "Rrp1b may therefore mediate tumor cell adhesion properties by altering intercellular and cell–ECM contacts in a Sipa1-dependent and Rap1-dependent manner." (PMID 18081427, 2007). "Average tumor weight was 240 mg ± 200 mg for the Rrp1b clones compared to 600 mg ± 270 mg for the β-galactosidase clone (p < 0.001), and average lung surface metastasis count being 5.7 ± 6.0 for the Rrp1b clones compared to 12.6 ± 8.4 for the β-galactosidase clone (p = 0.010)." (PMID 18081427, 2007). "Ribosomal RNA processing 1B (RRP1B) is involved in ribosomal production but the literature focuses on its effects on extracellular matrix gene expression, tumor growth, and metastasis of cancer cells." (PMID 32093603, 2020). "We have previously shown that a relationship between BRD4-LF, RRP1B and SIPA1 is critical for tumor progression and extracellular matrix regulation." (PMID 24260471, 2013). "Taken together, these data suggest that Rrp1b is a potential dual ECM and tumor progression candidate." (PMID 18081427, 2007). "In vitro expression of Rrp1b significantly altered ECM gene expression, tumor growth, and dissemination in metastasis assays." (PMID 18081427, 2007).
tumor (continued). "The peak linkage region of this locus encompasses both Rrp1b and a tumor growth and progression QTL, and rather remarkably, when we examined expression of transcripts within the peak eQTL linkage region, Rrp1b was highly correlated with metastasis-predictive ECM gene expression." (PMID 18081427, 2007).
cancer (7 papers, 2007 to 2025). A tumor composed of atypical neoplastic, often pleomorphic cells that invade other tissues. "There are few studies evaluating the associations of RRP1B rs9306160 polymorphisms with cancer risk or clinical data." (PMID 38610928, 2024). "Based on the transcriptomic data of TCGA pan-cancer cohorts, the expression of RRP1B, RRP1, MAZ, DUS1L, and HGH1 was identified to correlate positively with the expression of SLC19A1 in 40 types of cancers." (PMID 40149548, 2025). "While the molecular understanding of RRP1B as a potential modifier of metastasis is present, there is a scarcity of reports concerning the impact of host genetic factors on various cancer progressions and metastases." (PMID 38610928, 2024). "We recognize that the complexity of cancer biology extends beyond well-established oncogenes, and exploring genes like RRP1B allows us to broaden our understanding of the disease." (PMID 38610928, 2024). "It is proposed that RRP1B is targeted by miR-320a and contributes to cancer survival." (PMID 38610928, 2024). "In CLBC cells, DOCK1 mediates cell growth and motility through down-regulating the expression of claudin-1 via the RRP1B–DNMT–claudin-1 pathway, and claudin-1 serves as an important effector in DOCK1-mediated cancer progression and metastasis." (PMID 31717460, 2019). "Furthermore, RRP1B interacts with the protein BRD4, a transcriptional and epigenetic regulator that holds a pivotal role in cancer development." (PMID 38610928, 2024). "ALYREF directly interacts with RRP1B, so the increased expression of ALYREF in cancer cells may titrate away RRP1B allowing metastasis to develop uninterrupted." (PMID 27679854, 2016).
RRP1B also shares sentences with these, for which no sentence is quoted: breast tumors (1 paper); cardiovascular disease (1); coronary artery disease (1); laryngeal tumor (1); liver cancer (1); non-small cell lung carcinoma (1); thyroid cancer (1).